CACNA2D3 (calcium voltage-gated channel auxiliary subunit alpha2delta 3)
Diseases named in the same sentence as CACNA2D3 in open-access papers (continued):
Sharing a sentence is not in itself a finding about the gene and the disease.
nicotine dependence (2 papers, 2020 to 2024). Physical and psychological dependence on nicotine. "Like CACNA2D2 and CACNA2D3 have been reported as GWAS candidates associated with nicotine dependence, CACNA2D1 has been involved in increased presynaptic NMDAR activity associated with hyperalgesia following chronic morphine." (PMID 38338915, 2024). "The genome-wide meta-analysis on nicotine dependence has reported the protective role of CACNA2D3 in nicotine dependence for African Americans." (PMID 38338915, 2024). "Nevertheless, more recently, CACNA2D3 has been linked to neurodevelopmental disorders such as SCZ, BPD, MDD, nicotine dependence (ND), and especially to ASD (CACNA2D3)." (PMID 32607809, 2020). "A previously identified GWAS variant of CACNA2D3, in which the SNP is in the intron region, was not prioritized for further validation, but it was reported that this variant was associated with reduced expression levels in three human brain tissues and was associated with nicotine dependence." (PMID 38338915, 2024).
aneurysm (1 paper, 2025). Bulging or ballooning in an area of an artery secondary to arterial wall weakening. "Additionally, transcriptome data reveal that CACNA2D3 is markedly upregulated in the walls of ruptured IAs, whereas ANO6 exhibits significantly higher expression in unruptured aneurysm walls." (PMID 40388745, 2025).
arrhythmogenic right ventricular cardiomyopathy (1 paper, 2020). "Cacna2d3 is associated with arrhythmogenic right ventricular cardiomyopathy (p-value = 0.0008)." (PMID 32168507, 2020).
B-cell neoplasm (1 paper, 2018). A group of heterogeneous lymphoid tumors generally expressing one or more B-cell antigens or representing malignant transformations of B-lymphocytes. "FISH analyses narrowed one breakpoint down to region 3p21 located between the genes CACNA2D2 and CACNA2D3, and the other breakpoint to the IGH locus at 14q32 which is recurrently altered in B-cell neoplasms." (PMID 30680064, 2018).
Brachycephaly (1 paper, 2019). An abnormality of skull shape characterized by a decreased anterior-posterior diameter. "A few of these loci, such as CACNA2D3 and MSRB3, have been previously implicated in human reproductive pathologies, whereas others have been associated with domestication-related traits, including brachycephaly (SMOC2) and coat curl (KRT71)." (PMID 31263560, 2019).
COVID-19 (1 paper, 2024). A disease caused by infection with severe acute respiratory syndrome coronavirus 2. "In contrast, the expression of genes CACNA2D3 and KLRB1 has decreased in severe COVID-19 patients." (PMID 38262689, 2024).
dengue (1 paper, 2019). "In addition, host genetic markers, such as the genes LOC286087, MYOM2, CACNA2D3, PSPH, SMAD5, SLC4A4D, and CD244 molecule, with reduced expression in DHF than in DF can be used as predictors of severe dengue." (PMID 31192066, 2019).
Epileptic encephalopathy (1 paper, 2020). A condition in which epileptiform abnormalities are believed to contribute to the progressive disturbance in cerebral function. "In addition, mutations of calcium channels have been found in ASD, for example, CACNA1A rs7249246/rs12609735 were associated with Chinese Han ASD, and CACNA1A mutations in Epileptic Encephalopathy, gain of function of CACNA1C in Timothy syndrome with ASD and recurring CNVs of CACNA2D3." (PMID 33338084, 2020).
esophageal cancer (1 paper, 2019). A primary or metastatic malignant neoplasm involving the esophagus. "To analyze the relationship between the expression of CACNA2D3 and chemoresistance in ESCC, we screened microarray data predicting the response of esophageal cancer patients to neoadjuvant chemotherapy from the Gene Expression Omnibus (GSE45670)." (PMID 31001468, 2019).
hypertrophic cardiomyopathy (1 paper, 2023). A condition in which the myocardium is hypertrophied without an obvious cause. "In our study, the CACNA2D3 and CTBP1 gene was enriched in the Cardiac muscle contraction, Hypertrophic cardiomyopathy, and Notch signaling pathway." (PMID 37828092, 2023).
intracranial aneurysm (1 paper, 2025). "Transcriptome data from intracranial aneurysm samples confirmed significant differential expression of CACNA2D3 and ANO6 between ruptured and unruptured groups." (PMID 40388745, 2025).
leprosy (1 paper, 2026). Leprosy is a chronic infectious disease affecting primarily the skin and peripheral nervous system. "We confirmed that the SNP rs1449325 in CACNA2D3 was associated with leprosy per se protection in the overdominant model (ORoverdTC = 0.70; p = 0.00443) in Rio de Janeiro, which was then replicated in samples from Manaus and Rondonópolis." (PMID 42044188, 2026).
lymph node metastasis (1 paper, 2013). "Tissue microarray result showed that downregulation of CACNA2D3 was detected in (127/224, 56.7%) ESCCs, which was significantly associated with lymph node metastasis (P = 0.01), TNM staging (P = 0.003) and poor outcome of ESCC patients (P<0.05)." (PMID 23560067, 2013). "Clinical association analysis demonstrated that downregulation of CACNA2D3 was positively correlated with lymph node metastasis (P = 0.01) and advanced clinical staging (P = 0.003)." (PMID 23560067, 2013).
metastatic disease (1 paper, 2015). "Methylation-dependent silencing of CACNA2D3 was proposed as a biomarker for the risk of development of metastatic disease in breast cancer, where methylation correlated strongly with visceral and metastatic disease independent of α-estrogen receptor expression." (PMID 26010603, 2015).
nasopharyngitis (1 paper, 2018). An inflammatory process that affects the nasopharynx. "Among the six TSGs examined, the relative expression levels of CHFR, RIZ1, and CACNA2D3 in tissue samples were significantly decreased in NPC patients compared with those in nasopharyngitis patients (all P < 0.05)." (PMID 29764493, 2018).
squamous cell carcinoma (1 paper, 2016). A carcinoma arising from squamous epithelial cells. "Potential tumor suppressor genes, also found in other squamous cell carcinomas, have been discovered in the lost regions 2q33-q37.3 (PLCD4), 3p26.3-q11.1 (RBMS3, PLCD1, and CACNA2D3) and 11q12.2-q25 (CPT1A, CCND1, FGF4/FGF3, and PPP2R1B)." (PMID 26901676, 2016).
Stillbirth (1 paper, 2019). Death of the fetus in utero after at least 22 weeks of gestation. "We identified 12 genome-wide significant associations between these traits and genetic loci, including variants near CACNA2D3 with gestation length, MSRB3 and MSANTD1 with litter size, SMOC2 with cesarean section rate and UFM1 with stillbirth rate." (PMID 31263560, 2019).
substance dependence (1 paper, 2021). The psychological or physiological need to take a substance in order to experience its effects or to avoid the effects of its absence. "Genes located in substance dependence, Signal transduction and also nervous functions pathways were down‐regulated: Cacna2d3, Epha6, Nedd4l and Vav2." (PMID 34196487, 2021). "Genes located in substance dependence, signal transduction and nervous functions pathways were down‐regulated: Cacna2d3, Epha6, Nedd4l and Vav2." (PMID 34196487, 2021).
tumor (25 papers, 2009 to 2025). "An association between CACNA2D3 and both patient survival and tumor metastasis has been demonstrated in other cancers." (PMID 36046118, 2021). "Our previous study also identified CACNA2D3 as a tumor suppressor gene, and methylation of its promoter and allele deletion could inhibit its expression in ESCC." (PMID 31001468, 2019). "Whether the autophagic effect of Cacna2d3 is associated with its anti-tumor function remain to be explored." (PMID 30327467, 2018). "CACNA2D3 is an auxiliary member of the α-2/δ subunit triple family with voltage-dependent calcium channel complexes and plays a key role in tumor suppression." (PMID 40777122, 2025). "In a mouse xenograft model, the treatment with P4 also upregulated the expression of CACNA2D3 and attenuated tumor growth." (PMID 36230654, 2022). "By introducing mitochondria-mediated apoptosis, CACNA2D3 also plays a critical role in tumor suppression." (PMID 34941772, 2021). "In vivo experiments further showed that overexpression of CACNA2D3 enhanced cisplatin anti-tumor effects in a xenograft mouse model." (PMID 31001468, 2019). "The mean tumor size and weight in the CACNA2D3 overexpression group were significantly lower than those in the vector control group after cisplatin treatment." (PMID 31001468, 2019). "The tumor suppressive function of CACNA2D3 was characterized by both in vitro and in vivo tumorigenic assays, cell migration and invasion assays." (PMID 23560067, 2013). "Expression of CACNA2D3 was compared between tumor and their paired non-tumor tissues in 48 ESCC patients by quantitative real-time PCR." (PMID 23560067, 2013). "Kaplain-Meier analysis showed that overall survival rate of ESCC patients decreased as CACNA2D3 was downregulated in tumor tissues." (PMID 23560067, 2013). "The average expression level of CACNA2D3 was significantly reduced in tumor tissues compared with their paired non-tumor tissues (P<0.05)." (PMID 23560067, 2013). "In the present study, another candidate TSG, CACNA2D3 (calcium channel, voltage dependent, alpha-2/delta subunit 3) at 3p21.1, was characterized for its tumor suppressive function and mechanism." (PMID 23560067, 2013). "In this study, we studied the downregulation of CACNA2D3 and its tumor suppressive function and mechanism in ESCC." (PMID 23560067, 2013). "CACNA2D3 downregulation as well as other clinicopathologic features which were significant in univariate analysis (e.g. tumor differentiation, lymph nodes metastasis and TNM stage) were examined in multivariate analysis." (PMID 23560067, 2013). "Both in vitro and in vivo assays were used to characterize the potential tumor suppressive function of CACNA2D3." (PMID 23560067, 2013). "The region located between 3p21.3 and 3p14.3, deleted in both cell sub-lines, contains several established tumor suppressor genes including LTF, TDGF1, WNT5a, and RASSF, as well as candidate tumor suppressors such as CACNA2D3, GNAI2, and SEMA3B." (PMID 23951555, 2013). "Expression of CACNA2D3 in protein level was studied by IHC using a tissue microarray containing 300 pairs (tumor and non-tumor tissues) of primary ESCCs." (PMID 23560067, 2013). "We also demonstrate that CACNA2D3 has strong tumor suppressive function through the cell cycle arrest and induction of apoptosis." (PMID 23560067, 2013). "Overexpression of CACNA2D3 also decreases tumor growth in a mouse xenograft model." (PMID 36230654, 2022). "Overexpression of CACNA2D3 in vitro significantly inhibits tumor cell proliferation and migration." (PMID 35045818, 2022). "Our previous study identified CACNA2D3 as a novel tumor suppressor gene for ESCC." (PMID 31001468, 2019). "Higher expression of CACNA2D3 in tumor tissue was observed in 13/224 (5.8%) of ESCCs." (PMID 23560067, 2013). "Loss of CACNA2D3 allele could be observed in 2 cell lines (KYSE410 and KYSE510) and 1 primary ESCC tumor with the downregulation of CACNA2D3." (PMID 23560067, 2013).
tumor (continued). "The results found that CACNA2D3 could inhibit cell growth, focus formation, colony formation in soft agar and tumor formation in nude mice." (PMID 23560067, 2013). "Previously, we showed that CACNA2D3 (voltage-dependent subunit alpha 2 delta 3 of a calcium channel complex) was significantly downregulated and functioned as a tumor suppressor in ESCC, but its role in the chemosensitivity of ESCC to cisplatin remained unknown." (PMID 31001468, 2019). "Moreover, CACNA2D3 increased chemosensitivity to cisplatin in cell experiments and xenograft tumors, indicating that it could be used as a tumor marker to predict and improve patients' response to cisplatin." (PMID 31001468, 2019). "However, it could be useful to investigate whether CACNA2D3 is a tumor suppressor in OAC." (PMID 36046118, 2021). "The three transcripts, CACNA2D3, CNTNAP2 and TFAP2B, showed a 4–5 times lower expression in unfavourable tumour types." (PMID 19686582, 2009). "CACNA2D3 and DACT2 are tumor suppressor genes and epigenetic inactivation of these genes are linked with progression of various cancer types, but suppression of these genes might be identified with progression of pituitary prolactinoma." (PMID 33709028, 2021). "The result showed that the downregulation of CACNA2D3 was detected in 24/48 (50%) of ESCC tumor tissues compared with their paired non-tumor tissues." (PMID 23560067, 2013). "Downregulation of CACNA2D3 was detected in 127/224 (56.7%) informative ESCC tumor tissues compared with their paired non-tumor tissues." (PMID 23560067, 2013).
cancer (12 papers, 2006 to 2025). A tumor composed of atypical neoplastic, often pleomorphic cells that invade other tissues. "Furthermore, CACNA2D3 methylation is associated with shorter survival, making it a useful prognostic marker for this type of cancer." (PMID 36520928, 2022). "CACNA2D3 (calcium voltage-gated channel auxiliary subunit alpha2delta3) plays an important role in canceration." (PMID 35045818, 2022). "It would also be valuable to know whether there are any synergistic effects between CACNA2D4 and CACNA2D3; the literature points to each gene having opposing roles in the cancers." (PMID 36046118, 2021). "In addition, Prickle2 and Cacna2d3 are two potential tumor suppressor genes in the development and progression of carcinoma." (PMID 32245399, 2020). "Overall, the candidate gene set was significantly enriched for known cancer census genes (e.g. SGK1, MECOM, PRKCB) and known transcription co/factors (e.g. CACNA2D3, BMP4)." (PMID 36624125, 2023). "After looking through papers, only 4 genes of these prognostic markers have been verified to be relavant with according cancers, including CCL4 in COAD, CACNA2D3 and SMO in ESCA, and IL23R in LUAD." (PMID 31888612, 2019). "On the other hand, “hub genes” of four other modules contain POU2F3 (↑), CENPH (↑), PCSK6 (↑) and HERC2 (↑), BCAR3 (↑), DOHH (↑), NLK (↑), SCN2A (↑), CACNA2D3 (↓) and CTNND2 (↓), which were commonly reported related to cancer." (PMID 27602771, 2016).
cardiac disease (1 paper, 2014). "Because high blood pressure is a major risk factor for cardiac disease, CACNA2D3 could also lead to blood pressure." (PMID 25519404, 2014). "CACNA2D3 has been reported to be associated with cardiac disease." (PMID 25519404, 2014).
CACNA2D3 also shares sentences with these, for which no sentence is quoted: nasopharyngeal carcinoma (4 papers); lung carcinoma (3); neurodevelopmental disorder (2); neurological disorders (2); anemia (1); anxiety disorder (1); Ataxia (1); atopic dermatitis (1); bipolar disorder (1); cardiomyopathies (1); developmental and epileptic encephalopathy (1); diabetes (1); gallbladder cancer (1); Insulin resistance (1); leukemia (1); melanoma (1); non-small cell lung carcinoma (1); oesophageal cancer (1); pancreatic cancer (1); prostate carcinoma (1); sarcoma (1); Timothy syndrome (1); type 2 diabetes (1).